CRP (C-reactive protein)
Diseases named in the same sentence as CRP in open-access papers (continued):
Sharing a sentence is not in itself a finding about the gene and the disease.
rheumatoid arthritis (continued). "Studies have shown that NMR correlates with rheumatoid arthritis disease activity and aligns with classical markers such as C-reactive protein (CRP), erythrocyte sedimentation rate (ESR), and rheumatoid factor (RF)." (PMID 40709173, 2025). "Anakinra is a recombinant human IL-1 receptor antagonist (IL-1ra) authorized for use in treating rheumatoid arthritis and other illnesses characterized by inflammation and has been found to reduce inflammatory markers such as CRP, ferritin, D-dimers, and IL-6." (PMID 39493146, 2024). "The biosynthesis of C-reactive protein (CRP) in the liver is increased in inflammatory diseases including rheumatoid arthritis." (PMID 38650931, 2024). "Several phenotypes (Crohn’s disease, ulcerative colitis, rheumatoid arthritis, multiple sclerosis, vitiligo, CRP, and WBC) indicated significant heterogeneity of SNP instruments (IVW heterogeneity statistic p < 0.05/21), indicative of horizontal pleiotropy." (PMID 38561342, 2024). "Elevated levels of CRP indicate systemic inflammatory conditions such as rheumatoid arthritis, lupus or other autoimmune disorders." (PMID 39498386, 2024). "This cost-effectiveness makes MCP-1 a viable alternative to CRP, a traditional biomarker, for evaluating the disease activity of rheumatoid arthritis in clinical settings." (PMID 39518927, 2024). "Several conditions and situations can increase CRP levels, including infections, chronic inflammation such as rheumatoid arthritis, inflammatory bowel diseases, autoimmune diseases, and chronic obstructive airway diseases." (PMID 38983990, 2024). "Using a ML algorithm, researchers aimed to predict the Disease Activity Score-28 for Rheumatoid Arthritis with CRP (DAS28-CRP) one year into the future." (PMID 39518698, 2024). "Clinical measurement of blood CRP level is indicated for determining disease severity and prognosis for many diseases, including Crohn’s disease, rheumatoid arthritis and even some types of cancer." (PMID 39327635, 2024). "The Disease Activity Score-28 for Rheumatoid Arthritis with CRP (DAS28-CRP) was used as a tool to quantify disease activity." (PMID 37768405, 2023). "N = 90 patients with cardiovascular disease and/or rheumatoid arthritis and/or OA and high levels of CRP (>1.0 mg/dL)." (PMID 37298291, 2023). "CRP does have utility for assessment of disease severity and progression in some conditions such as rheumatoid arthritis, malignancy, and IBD." (PMID 37476185, 2023). "Previous data remind us that baseline CRP level is a predictor of CV mortality and CV events in rheumatoid arthritis patients." (PMID 37143665, 2023). "In rheumatoid arthritis, an intronic variant of ANKRD55 was associated with the disease, and there was a significant correlation between CRP levels and the variant." (PMID 37238156, 2023). "For example, plasma exosomes can inhibit CRP production in fibroblasts and induce rheumatoid arthritis." (PMID 37124494, 2023). "Modulation of CRP levels and vigilant assessment can also prevent autoimmune disorders such as rheumatoid arthritis, where elevated CRP levels are suggestive of aggravation of symptoms." (PMID 39554800, 2023). "It is known that serum CRP, which is induced by IL-6, is less likely to be elevated in patients with rheumatoid arthritis who are being treated with anti-IL-6 receptor antibody preparations." (PMID 38002777, 2023). "Correlations of a similar magnitude to those found in our study have been described between serum S100A8/A9 and other APPs such as CRP (r = 0.55) in patients with rheumatoid arthritis." (PMID 37627347, 2023). "Fifth, our study demonstrates that genetic prediction of rheumatoid arthritis mediated by C-reactive protein is 3.7%, which is very low." (PMID 36589832, 2022). "The mean Disease Activity Score-28 for Rheumatoid Arthritis with C-Reactive Protein (DAS28-CRP) was higher in patients who continued smoking than in patients who quit smoking (4.9 vs 2.9, respectively; MD: −2.0; 95% CI: −2.3 to −1.7)." (PMID 36520847, 2022).
rheumatoid arthritis (continued). "In adult rheumatoid arthritis, CRP half-life is 19 h; as much as 3 days has been reported in other diseases." (PMID 36517828, 2022). "Disease activity score (DAS28), a tool required to calculate disease activity in newly diagnosed rheumatoid arthritis patients, assesses serum CRP levels along with 28 specified joints and a visual analog scale for global function." (PMID 36381804, 2022). "Previous studies in IBD and rheumatoid arthritis reported inverse correlations between cDPP and cFAP activity with inflammation, indicated by CRP concentrations." (PMID 35060938, 2022). "The cohort in the present study does not include information on detailed complications or past history that can be affected to the serum CRP level, such as inflammatory bowel disease, lupus, rheumatoid arthritis, and infections." (PMID 36428750, 2022). "TJC and DAS 28 CRP were measured in patients with rheumatoid arthritis and psoriatic arthritis alone." (PMID 35077469, 2022). "CRP exhibits elevated expression during inflammatory conditions such as rheumatoid arthritis, some cardiovascular diseases, and infection." (PMID 35572999, 2022). "Several SNPs used as instruments in our analyses have also been associated with other inflammation-related traits, such as white blood cell count, CRP, rheumatoid arthritis and eczema, strengthening their biological relevance as instrumental variables." (PMID 35012533, 2022). "The mean blood copper level in rheumatoid arthritis patients was significantly higher than control healthy patients; the blood copper level was positively correlated with the C-reactive protein level and erythrocyte sedimentation rate." (PMID 36145052, 2022). "Deutsch recruited participants with diagnosed cardiovascular disease and/or rheumatoid arthritis and/or OA with increased CRP concentrations." (PMID 35880828, 2022). "The proportion of genetically predicted rheumatoid arthritis mediated by C-reactive protein was 3.7% (95%CI 0.1%−7.3%)." (PMID 36589832, 2022). "Clinical trials showed that anti-IL-17 antibodies significantly reduced rheumatoid arthritis (RA) signs and symptoms and C-reactive protein levels." (PMID 34239943, 2021). "A significant relationship between rheumatoid arthritis Disease Activity Score-28 or C-reactive protein and sleep quality parameters has been reported by several studies." (PMID 34933686, 2021). "Baricitinib, a JAK inhibitor blocking central inflammatory signaling pathways, was recently shown to decrease systemic inflammation biomarkers, such as IL-6, CRP, as well as adiponectin, in rheumatoid arthritis patients." (PMID 33499006, 2021). "Meanwhile, elevated TNF-α and IL-6 stimulate the expression of rheumatoid arthritis-related proteins such as C-reactive protein." (PMID 34108880, 2021). "These intriguing results are in line with a novel study using t-VNS in 5 days, showing reduced disease activity (DAS28-CRP), CRP, and interferon-γ in patients with rheumatoid arthritis and flare." (PMID 34135691, 2021). "In acute disease, plasma IL‐38 correlates with CRP in rheumatoid arthritis patients, and is elevated in comparison to healthy controls." (PMID 33125159, 2021). "Sarilumab, as an FDA-approved antibody medication for rheumatoid arthritis treatment, shows clinical improvement with decreased CRP level to patients with COVID-19 disease." (PMID 34880750, 2021). "Vitamin B-6 has also been associated with inflammation (CRP) in the NHANES study (2003-2004), and B-6 supplementation in rheumatoid arthritis patients has been shown to reduce levels of IL-6 and TNF-α." (PMID 34836049, 2021). "Elevated levels of C-reactive protein (CRP) in the blood are well known to often indicate increased inflammatory conditions, which may be caused by a wide variety of acute (e.g., infections) and chronic disorders (e.g., rheumatoid arthritis, inflammatory bowel disease)." (PMID 34103083, 2021).
rheumatoid arthritis (continued). "There is also evidence that oxidative stress correlates significantly with specific inflammatory biomarkers such as Tumour Necrosis Factor Alpha (TNF-α) and C-Reactive Protein (CRP) in individuals with rheumatoid arthritis." (PMID 32878326, 2020). "Nevertheless, it is noteworthy that conventional assessments of primary disease severity sometimes included a biomarker index of inflammation (e.g., the DAS28-CRP index used to assess rheumatoid arthritis severity includes CRP)." (PMID 31427751, 2020). "Serum levels of SOST were significantly higher in patients with rheumatoid arthritis and correlated with disease severity, bone erosion and inflammatory markers such as C-reactive protein (CRP)." (PMID 33218086, 2020). "C-reactive protein levels have been shown to predict prolonged QT intervals in patients with systemic lupus erythematosus, rheumatoid arthritis and patients with other connective tissue diseases." (PMID 32050594, 2020). "For example, Yujie41 found that elevated RDW is correlated with inflammatory markers such as CRP and ESR in patients with rheumatoid arthritis, and Zhide13 show that RDW is up‐regulated and positively associated with ESR, CRP, IgM, and SLEDAI in SLE patients." (PMID 31978275, 2020). "Covering both fibrinogen and albumin, FAR reflected systemic inflammation in patients with rheumatoid arthritis, which was comparable to C-reactive protein." (PMID 32879878, 2020). "In the present study, we analyzed outcomes in the placebo arms of 5 RCTs of rheumatoid arthritis, comparing CRP level, ESR, and subjective pain levels." (PMID 32936297, 2020). "For the biomarkers, in patients with rheumatoid arthritis, the accumulation of Alloprevotella is positively correlated with the biomarker of the inflammatory response C-reactive protein." (PMID 32714401, 2020). "Of note, rheumatoid arthritis patients had elevated C-reactive protein (CRP) and lower goblet cell density compared to healthy subjects." (PMID 32820183, 2020). "Clinical characteristics such as disease duration, rheumatoid factor, anti-cyclic citrullinated peptide, erythrocyte sedimentation rate, C-reactive protein, Disease Activity Score of 28 joints, Fatigue Severity Scale, Rheumatoid Arthritis Impact of Disease." (PMID 31024773, 2019). "Baricitinib is a JAK 1/2 inhibitor approved in the USA, EU, and Japan for rheumatoid arthritis, demonstrating potent inhibition of IL-6, D-dimer, CRP, TNF-α, IFN-α/β, and other pro-inflammatory cytokines." (PMID 31561750, 2019). "C-reactive protein (CRP) is a traditional biomarker which is elevated in inflammatory states including rheumatoid arthritis and infection." (PMID 31036824, 2019). "CRP, the most common inflammatory and acute phase protein indicator, is commonly used for evaluating disease activity in rheumatoid arthritis, although half the patients have normal CRP levels." (PMID 30658492, 2019). "C-reactive protein is a homopentameric acute-phase inflammatory protein that exhibits elevated expression during inflammatory conditions such as rheumatoid arthritis, some cardiovascular diseases, and infection." (PMID 29706967, 2018). "Given inflammation is major concern in rheumatoid arthritis, C reactive protein relationship with CV function should have been examined." (PMID 30057616, 2018). "C-reactive protein exhibits elevated expression during inflammatory conditions such as rheumatoid arthritis, some cardiovascular diseases, and infection." (PMID 29706967, 2018). "However, CRP level can be elevated by intracapsular fractures of the femoral neck from increase in inflammatory factors because of synovial membrane production and correlated with the severity of surgical or traumatic injury, underlying patients' conditions such as frailty or rheumatoid arthritis." (PMID 29854731, 2018).
rheumatoid arthritis (continued). "CRP is a homopentameric acute-phase inflammatory protein that exhibits elevated expression during inflammatory conditions, such as rheumatoid arthritis, some cardiovascular diseases, and infection." (PMID 30013561, 2018). "C-reactive protein (CRP) is an established marker of rheumatoid arthritis (RA) but with ill-defined actions in the pathogenesis." (PMID 29520264, 2018). "Otherwise, Selenium was also studied with C-reactive protein in many illnesses and the results demonstrated an important role of C-reactive protein in the acute phase response in several ones such as rheumatoid arthritis, lung cancer, adult T-cell leukemia." (PMID 29875918, 2018). "The increased level of IL-36α in serum from patients with rheumatoid arthritis is positively correlated with C-reactive protein (CRP)." (PMID 30356900, 2018). "TC genotype of miR-499 rs3746444 has been reported to be associated with higher C-reactive protein (CRP) and erythrocyte sedimentation rate (ESR) compared to CC and TT genotype in rheumatoid arthritis patients." (PMID 28301487, 2017). "Rheumatoid arthritis (RA) treat-to-target (T2T) regimens often use the disease activity score (28 joints) incorporating C-reactive protein (DAS28CRP) as an outcome measure." (PMID 29065903, 2017). "The level of anti-FRP antibodies is correlated with inflammatory signs such as increasing erythrocyte sedimentation rate (ESR) and over-expression of serum C-reactive protein (CRP) in rheumatoid arthritis patients." (PMID 28498809, 2017). "The numbers of circulating mDCs and pDCs were also shown by others to be reduced in the blood of rheumatoid arthritis patients and to inversely correlate with serum CRP levels." (PMID 28232832, 2017). "In PsA, the most common inflammatory indicators (ESR and CRP) used for the evaluation of disease activity in rheumatoid arthritis are within normal levels in half of the patients." (PMID 28356155, 2017). "In the study, it was shown that antibodies to ox-LDL were correlated significantly with ESR and CRP in patients with early rheumatoid arthritis and suggested that the occurrence of these antibodies must be related to inflammation." (PMID 28883908, 2017). "RDW has also been correlated with soluble tumor necrosis factor receptor and CRP in the settings of rheumatoid arthritis and heart failure." (PMID 27906969, 2016). "Recent studies have shown that P. cuspidatum has an anti-inflammatory effect in rheumatoid arthritis and hepatitis models by inhibiting C-Reactive Protein (CRP) and inflammation-related liver injuries." (PMID 26950148, 2016). "Of the four in the control group, one had a CRP within 1 mg of the cutoff point, two had a background of rheumatoid arthritis and were receiving steroids, and one had a periprosthetic fracture and concomitant lower limb cellulitis at the time of admission." (PMID 26583149, 2015). "Traditionally CRP has been used to distinguish systemic inflammatory disorders such as rheumatoid arthritis from OA." (PMID 26245599, 2015). "CRP is mostly used to follow disease activity during the acute phase in patients with rheumatoid arthritis." (PMID 26925896, 2015). "The primary objective of this study was to evaluate and compare the immunodiagnostic significance and utility of anti-RA33 with anti-CCP, RF, and CRP in Saudi patients with rheumatoid arthritis." (PMID 25883991, 2015). "Studies of patients with rheumatoid arthritis (RA) document a correlation between C-reactive protein (CRP) blood concentration and worsening of RA symptoms." (PMID 25885521, 2015). "For instance, factor XIII A-subunit genotype was shown to influence C-reactive protein levels during inflammation in rheumatoid arthritis (RA)." (PMID 25142923, 2014). "C-reactive protein (CRP) is known to be elevated in active disease and to decrease upon effective treatment in SpA, but is less useful than in rheumatoid arthritis (RA) as two thirds of the SpA patients have normal CRP levels." (PMID 25135077, 2014).
rheumatoid arthritis (continued). "We aimed to investigate the possible association between seven CRP SNPs, their haplotypes and the serum levels of CRP, as well as DAS28 scores, in two cohorts of untreated active early rheumatoid arthritis (RA) patients followed during their initial treatment." (PMID 25359432, 2014). "The erythrocyte sedimentation rate (ESR) and C-reactive protein (CRP) are two commonly used measures of inflammation in rheumatoid arthritis (RA)." (PMID 25373740, 2014). "CRP levels have also been shown to be good markers for inflammation, bone degradation, and clinical well-being of patients with rheumatoid arthritis." (PMID 25114906, 2014). "IL32 levels showed positive correlations with tumor necrosis factor alpha, ESR, C-reactive protein, replication factor, and Disease Activity Score 28 genes in rheumatoid arthritis." (PMID 25100201, 2014). "It was observed that serum amyloid A is even more sensitive than CRP in response to the inflammatory lesion of rheumatoid arthritis." (PMID 23418544, 2013). "The drug sponsors have announced that this first CRP inhibitor will be employed as an early proof of concept for the target in a variety of diseases, including multiple myeloma and rheumatoid arthritis." (PMID 22989709, 2012). "By studying patients with rheumatoid arthritis we made use of the historical tendency to record the erythrocyte sedimentation rate (ESR) alongside CRP as an alternative and independent marker of inflammation." (PMID 20877716, 2010). "In a clinical study, by the same researchers, plasma levels of DPPIV/CD26 from rheumatoid arthritis patients were significantly decreased when compared to those from osteoarthritis patients and inversely correlated with C-reactive protein levels." (PMID 20520837, 2010). "Although patients with chronic inflammatory diseases, such as rheumatoid arthritis, have raised levels of CRP, levels of CRP are still highly variable." (PMID 20877716, 2010). "We have studied genetic determinants of acute-phase CRP in patients with rheumatoid arthritis, a chronic inflammatory disease characterised by a marked acute-phase response." (PMID 20877716, 2010). "As expected, rheumatoid nodules were associated with disease duration, smoking, HAQ score, JSN, RF, anti-CCP antibodies, elevated CRP levels, and methotrexate use." (PMID 20444266, 2010). "With respect to CRP, for example, it is interesting that lower baseline CRP concentrations predict an ACR50 response for patients with rheumatoid arthritis, which is in contrast to our findings for patients with PsA." (PMID 19815494, 2010). "Methods: 35 patients with early rheumatoid arthritis – below 12 months from the onset, naive for DMARDs, underwent clinical standard examination as well as serum determinations for CRP, RF, anti-CCP2 antibodies and VEGF." (PMID 20108506, 2008). "Among 7,121 cases with 'newly-diagnosed' rheumatoid arthritis, 3,576 cases had at least one valid CRP measurement of which 2,421 (34% of the initial sample) had a 6-month run-in prior to their first rheumatoid presentation." (PMID 18983663, 2008). "In this study, we sought to examine effect of both average CRP and CRP change on progression to total joint replacement using routine laboratory data recorded in general practice among patients diagnosed with rheumatoid arthritis." (PMID 18983663, 2008). "Abnormal vitamin B6 status in rheumatoid arthritis has been associated with spontaneous tumor necrosis factor (TNF)-α production and markers of inflammation, including C-reactive protein (CRP) and erythrocyte sedimentation rate." (PMID 16277693, 2005). "Abnormal vitamin B6 status in rheumatoid arthritis has been associated with spontaneous tumor necrosis factor (TNF)-α production and markers of inflammation, including C-reactive protein and erythrocyte sedimentation rate." (PMID 16277693, 2005).